EVA1B (eva-1 homolog B)
Synonyms: C1orf78; FAM176B; FLJ10647
Tractability: Antibody: UniProt predicts a signal peptide or a membrane-spanning region; the Human Protein Atlas places it where antibodies can reach.
Gene: Protein-coding gene on chromosome 1 (36,322,030 to 36,324,154, reverse strand). Ensembl gene ENSG00000142694.
Subcellular location: Membrane
Subcellular location (Human Protein Atlas): Plasma membrane; Cytosol; Nucleoplasm
Gene Ontology:
Molecular function: protein binding
Cellular component: membrane
Genetic constraint (gnomAD): Loss-of-function variants: 7 observed, 4.89 expected, observed/expected ratio (o/e) 1.43, 90% interval 0.77 to 1.92. That is too few expected variants to judge how well the gene tolerates losing a copy. Missense variants: 263 observed, 205.03 expected, observed/expected ratio (o/e) 1.28, 90% interval 1.16 to 1.42. Synonymous variants: 124 observed, 89.57 expected, observed/expected ratio (o/e) 1.38, 90% interval 1.2 to 1.61.
Homologues: Orthologues: macaque EVA1B (99% identical), chimpanzee EVA1B (99% identical), pig EVA1B (95% identical), dog EVA1B (94% identical), guinea pig EVA1B (92% identical), mouse Eva1b (90% identical), zebrafish eva1bb (51% identical). Paralogues in human: EVA1A (44% identical).
Diseases named in the same sentence as EVA1B in open-access papers:
EVA1B is named in the same sentence as 6 diseases in open-access papers, as found by Europe PMC text mining. Sharing a sentence is not in itself a finding about the gene and the disease. The quoted sentences say what the papers report.
glioma (6 papers, 2021 to 2024). A benign or malignant brain and spinal cord tumor that arises from glial cells (astrocytes, oligodendrocytes, ependymal cells). "The findings of several recent studies have indicated that OLFML3, EVA1B, and FERMT3 are potential prognostic markers for glioma, which are significantly associated with poor prognosis and tumor immune microenvironment." (PMID 38686055, 2024). "This association indicates that two member of EVA family, EVA1B and EVA1C, might have a role in prognosticating elevated levels of immune infiltration within glioma." (PMID 37808305, 2023). "High expression of EVA1B is bound up closely with high infiltration levels of T cells, macrophages, and neutrophils in cancer tissues, and high expression of this gene implies poor prognosis in glioma patients." (PMID 36267313, 2022). "Studies have shown that EVA1B expression is upregulated in colon cancer and glioma." (PMID 36531485, 2022). "Previous research proposed the upregulation of EVA1B in glioma." (PMID 35250982, 2022). "Furthermore, multivariate analysis indicated that EVA1B is an independent prognostic biomarker for glioma." (PMID 33889156, 2021). "Importantly, EVA1B overexpression was associated with a higher infiltration level of CD4+ T cells, CD8+ T cells, B cells, macrophages, and neutrophils in glioma." (PMID 33889156, 2021). "Importantly, EVA1B overexpression was associated with the immune infiltration levels of immune cells including B cells, CD4+ T cells, CD8+ T cells, macrophages, and neutrophils, and strongly with the overall immune infiltration levels of glioma." (PMID 33889156, 2021).
colorectal cancer (1 paper, 2022). A primary or metastatic malignant neoplasm that affects the colon or rectum. "Herein, our study was conducted to investigate the role of EVA1B in colorectal cancer (CRC) progression and prognosis." (PMID 35250982, 2022).
tumor (4 papers, 2021 to 2024). "This study was conducted to investigate the correlation of EVA1B expression with prognosis, tumor immune and pharmacogenomic features in CRC." (PMID 35250982, 2022). "This contrasts with our finding, perhaps PSME2 and EVA1B possess cancer specific, and whether the regulation of these two genes also involves autophagy and tumor immune regulation in this study remains to be further explored." (PMID 36267313, 2022). "Additionally, high EVA1B expression was correlated to increased stromal and immune score as well as reduced tumor purity in CRC." (PMID 35250982, 2022). "The functional role of EVA1B in tumor immunity requires in-depth experimental verification." (PMID 35250982, 2022).
cancer (3 papers, 2019 to 2022). A tumor composed of atypical neoplastic, often pleomorphic cells that invade other tissues. "This study presented an integrative analysis of molecular characteristics, oncogenic roles, and relevant immune and pharmacogenomic features of EVA1B across pan-cancer, especially CRC." (PMID 35250982, 2022). "Pan-cancer analysis was conducted to analyze expression, genetic and epigenetic alterations, and immunological characteristics of EVA1B." (PMID 35250982, 2022). "There were prominently enhanced activities of most steps within cancer immunity cycle in high EVA1B expression subpopulation." (PMID 35250982, 2022). "Our further analysis demonstrated that EVA1B upregulation was correlated to enhanced immune cell infiltration, increased stromal and immune activation, and elevated activities of cancer immunity cycle." (PMID 35250982, 2022). "We applied a hard filter to the GSMs and finally selected six genes (CLDN3, DECR2, EVA1B, NME4, NTSR1 and XPNPEP3) associated with epigenetic regulation, differentiation and cancer (Pearson’s correlation test; p-value ≤ 0.001)." (PMID 31040866, 2019). "Thereafter, we analyzed the immunological characteristics of EVA1B across pan-cancer." (PMID 35250982, 2022). "EVA1B expression presented a remarkable upregulation in most cancer types, especially CRC." (PMID 35250982, 2022). "Additionally, the interactions of EVA1B expression with cancer immunity cycle and known biological processes were evaluated across CRC specimens." (PMID 35250982, 2022). "Our data demonstrated the remarkable upregulation of EVA1B expression in most cancer types." (PMID 35250982, 2022). "EVA1B expression was significantly correlated to DNA methyltransferases, DNA mismatch repair genes, m6A regulators, TMB, and MSI across pan-cancer." (PMID 35250982, 2022). "Our data suggested that EVA1B was remarkably correlated to immune cell infiltration, MCH molecules, chemokines, immunostimulatory factors, receptors, and immune checkpoint molecules across pan-cancer." (PMID 35250982, 2022). "We noted that EVA1B presented negative interactions with four major DNA methyltransferases containing DNMT1, DNMT2, DNMT3A, and DNMT3B in most cancer types." (PMID 35250982, 2022).
EVA1B also shares sentences with these, for which no sentence is quoted: colon cancer (1 paper); Pan (1).